Y_RNA (Y RNA )
Gene: Miscellaneous RNA gene on chromosome 7 (100,330,777 to 100,330,877, reverse strand). Ensembl gene ENSG00000201913.
Homologues: Orthologues: chimpanzee Y_RNA (100% identical), pig Y_RNA (76% identical). Paralogues in human: Y_RNA (98% identical), Y_RNA (94% identical), Y_RNA (93% identical), Y_RNA (91% identical), Y_RNA (89% identical), Y_RNA (87% identical), RNY3 (86% identical), RNY3P12 (86% identical), Y_RNA (86% identical), Y_RNA (85% identical), RNY3P1 (84% identical), RNY3P5 (84% identical), and 98 more.